SHBG (sex hormone binding globulin)
Diseases named in the same sentence as SHBG in open-access papers (continued):
Sharing a sentence is not in itself a finding about the gene and the disease.
alcohol use disorder (3 papers, 2024 to 2025). "Previously, we showed that SHBG mediated the associations of total testosterone with alcohol consumption and alcohol use disorder in both males and females, but it acted as a moderator of these same associations only in males." (PMID 40766921, 2025). "We determined that SHBG moderated the associations of total testosterone with both alcohol consumption and alcohol use disorder in males only, whereas in both females and males, SHBG mediated these same associations." (PMID 38464231, 2024). "Alcohol consumption behaviors and alcohol use disorder risk and presentation differ by sex, and are associated with blood concentrations of the steroid sex hormones, testosterone and estradiol, and their regulatory binding proteins, sex hormone binding globulin (SHBG) and albumin." (PMID 40766921, 2025). "Males with a history of alcohol addiction show an increase in both total testosterone and estrogens, but their bioavailability is lower due to the upregulation of SHBG production, thus suggesting that this binding protein imposes a positive effect on alcohol abuse and vice versa." (PMID 39590862, 2024). "However, the role and mechanisms involved in the dysregulated production of SHBG under alcohol abuse are still unknown." (PMID 39590862, 2024).
chronic heart failure (3 papers, 2022 to 2025). "Furthermore, studies in male patients with chronic heart failure showed a decrease in serum dehydroepiandrostenedione sulfate (DHEAS) and E2 as well as an increase in the sex hormone-binding globulin (SHBG) levels." (PMID 39124622, 2024).
Cognitive impairment (3 papers, 2017 to 2025). Abnormal cognition is characterized by deficits in thinking, reasoning, or remembering. "Increased levels of Hcy and SHBG and decreased leptin are strongly associated with the occurrence of cognitive impairment in SCZ cases." (PMID 39554652, 2024). "All these are evidence for the close relationship between an elevated SHBG level and cognitive impairment in patients with SCZ." (PMID 39554652, 2024). "When cognitive impairment occurs, patients with SCZ seem to have significantly increased Hcy and SHBG and reduced leptin." (PMID 39554652, 2024).
cryptorchidism (3 papers, 2008 to 2022). The failure of one or both testes of a male fetus to descend from the abdomen into the scrotum during the late part of pregnancy. "Among recent findings, higher prevalence of cryptorchidism and lower serum concentrations of inhibin B, follicle-stimulating hormone (FSH), and sex hormone–binding globulin (SHBG) and smaller testicular volumes at 3 months of age were recently reported for Danish boys, compared with Finnish boys." (PMID 18414644, 2008). "Our study shows that the severity of cryptorchidism plays a role for serum reproductive hormone levels during puberty, in particular with respect to FSH and inhibin B, whereas LH, testosterone, SHBG, and growth factors were not affected." (PMID 36073163, 2022).
cyst (3 papers, 2022 to 2024). A sac-like closed membranous structure that may be empty or contain fluid or amorphous material. "The concentration of SHBG also correlated with cyst volume, but testosterone did so only sub-significantly." (PMID 35659255, 2022). "Similarly, the cyst fluid concentration of SHBG and albumin, both of which may carry testosterone, correlated with tumor volume." (PMID 35659255, 2022). "Duration of methylprednisolone treatment did not correlate with cyst fluid concentrations of apolipoprotein A-I (r = 0.03) or albumin (r = 0.005), but it correlated inversely with SHBG (r = − 0.50; p = 0.011)." (PMID 35659255, 2022). "The level of SHBG was not significantly different in cyst fluid and serum." (PMID 35659255, 2022).
eating disorder (3 papers, 2015 to 2022). A broad group of psychological disorders with abnormal eating behaviors leading to physiological effects from overeating or insufficient food intake. "SHBG has been related to psychopathology in patients with eating disorders, who have also been reported to show reduced perfusion." (PMID 26356576, 2015).
hyperestrogenism (3 papers, 2024 to 2025). Abnormally high level of estrogen. "Hyperestrogenism that occurs in obese adolescents due to both amplified aromatization and low SHBG (which increases free estrogens), impairs SC metabolism, leading to increased glucose uptake but reduced lactate export, which is of pivotal importance for GC physiology." (PMID 38961093, 2024).
hypertrichosis (3 papers, 2014 to 2018). Excessive hair growth anywhere on the body. "There are also studies on the efficacy of oral contraceptives containing DRSP or CPA in the treatment of hypertrichosis that show a significant reduction in circulating androgen levels after a 6–12 month treatment and a significant increase in SHBG." (PMID 29462872, 2018). "We observed that girls with hypertrichosis who harbor haplotypes 3–5 have lower SHBG concentrations compared to controls with the same haplotype." (PMID 24745883, 2014). "Serum gonadotropins and sex steroids were similar in both groups, but SHBG was significantly lower in the girls with hypertrichosis (71.1 ± 2.9 vs 81.9 ± 3.0 nmol/L, p < 0.02)." (PMID 24745883, 2014). "Girls with hypertrichosis exhibited lower levels of SHBG, but had otherwise normal androgen levels." (PMID 24745883, 2014). "Interestingly, girls with hypertrichosis had significantly lower levels of SHBG than control girls (71.16 ± 16 vs 82 ± 15, p < 0.05)." (PMID 24745883, 2014). "We did not observe any differences in the androgen profile of both groups, except for lower levels of SHBG in the girls with hypertrichosis, although FAI was not different." (PMID 24745883, 2014).
hypoadiponectinemia (3 papers, 2014 to 2024). "In contrast, the levels of serum insulin and triglyceride further increased and the level of serum SHBG decreased in the puberty of PCOS offspring, and hypoadiponectinemia occurred much earlier than hyperandrogenemia." (PMID 33455575, 2021).
hypopituitarism (3 papers, 2021 to 2025). A condition of diminution or cessation of secretion of one or more hormones from the anterior pituitary gland. "The underlying cause of the decline in SHBG remains unclear, but it is thought to be primarily metabolic, rather than hormonal, as age-related reductions are also observed in boys with hypopituitarism." (PMID 40863113, 2025).
lipodystrophy (3 papers, 2013 to 2023). A congenital or acquired disorder characterized by abnormal loss or redistribution of the adipose tissue in the body. "Insulin correlated positively with SHBG in the insulin signaling subgroup, but negatively in lipodystrophy." (PMID 33901270, 2021). "Among patients with lipodystrophy, 45% (67/150) and 1.3% (2/150) had an SHBG level below or above the normal range, respectively; these proportions were 8% (4/49) and 27% (13/49) among patients with insulin signaling disorders, and 52% (11/21) and 0% (0/21) among patients with idiopathic SIR." (PMID 33901270, 2021).
morbid obesity (3 papers, 2021 to 2024). An excess of body weight, normally defined as an individual with a body mass index greater than 35 or a body weight greater than one hundred percent of ideal body weight. "Patients with morbid obesity who have undergone bariatric surgery show an increase in serum SHBG concentrations, which correlates closely with weight loss." (PMID 34805198, 2021).
Osteopenia (3 papers, 2021 to 2023). Osteopenia is a term to define bone density that is not normal but also not as low as osteoporosis. "In Saudi older men with osteopenia, SHBG was significantly inversely associated with BMD, notably at the spin." (PMID 38116310, 2023). "The findings demonstrate that SHBG levels were positively and significantly associated with age in both the control and osteopenia groups." (PMID 38116310, 2023). "In the osteopenia group, SHBG was positively correlated with age (r=0.33, p<0.05), while it was inversely correlated with BMD spine (r = -0.39, p<0.05) and T-score femur (r= -0.35, p<0.05) in the same group." (PMID 38116310, 2023). "A notable observation in the osteopenia group was the significant increase in SHBG and testosterone levels with advancing age." (PMID 38116310, 2023). "In conclusion, the prevalence of osteopenia is related to greater SHBG concentrations and decreased FAI." (PMID 38116310, 2023). "However, in the osteopenia group, SHBG levels exhibited a significant inverse correlation with T-score femur, BMD spine, and FAI." (PMID 38116310, 2023). "The study found that osteopenia patients had significantly increased SHBG and FSH levels, while FAI levels were reduced, which may explain bone loss." (PMID 38116310, 2023). "In terms of hormone levels, the osteopenia group displayed significantly lower free androgen index (FAI) and higher levels of SHBG and FSH compared to the control group." (PMID 38116310, 2023). "Those with osteopenia had significantly lower levels of FAI (p<0.05), and higher levels of SHBG (p<0.004) and FSH (p<0.005)." (PMID 38116310, 2023).
Ovarian Hyperandrogenism (3 papers, 2014 to 2021). Increased production of androgens by the ovaries. "Other choices to decrease ovarian hyperandrogenism, such as estroprogestatif pills, are provided because of their antigonadal action that inhibits LH resulting in lower ovarian androgens; their increasing sex hormone binding globulin is also recognized thus decreasing bioavailable testosterone." (PMID 26229697, 2015).
pituitary tumor (3 papers, 2016 to 2025). A benign or malignant neoplasm affecting the pituitary gland. "Lower concentrations of TSH (p = 0.022), fT3 (p < 0.001), SHBG (p = 0.021) were found in patients with pituitary tumours compared to the control group." (PMID 41234225, 2025). "These individuals may be recognized by their normal SHBG levels and distinguished from patients with TSH-producing pituitary tumors who have hyperthyroxinemia and high SHBG." (PMID 26761949, 2016).
preeclampsia (3 papers, 2008 to 2025). Preeclampsia is a hypertensive disorder of pregnancy that is characterized by new-onset hypertension with proteinuria presenting after 20 weeks of gestation, and depending on mild or severe forms may initially present with severe headache, visual disturbances, and hyperreflexia. "One study looking at first-trimester SHBG levels in 45 nulliparous women who developed preeclampsia found that levels were significantly reduced when compared with controls." (PMID 18790389, 2008).
prostate diseases (3 papers, 2024 to 2025). "Lastly, the fifth mode was a more male-expressed night owl subtype linked to elevated cardiovascular risks and male-special associations (e.g., higher testosterone level, lower SHBG level, prostate diseases)." (PMID 40766217, 2025).
urolithiasis (3 papers, 2014 to 2025). Stone(s) within the urinary tract. "In the Multivariate Mendelian Randomization (MVMR) analyses, the significant causal associations between estradiol, SHBG, tea intake, and alcoholic drinks per week with urolithiasis were robust even after adjusting for potential confounding variables." (PMID 37624788, 2023). "Tea intakes also maintained its significant causal association with urolithiasis after adjusting for estradiol (OR: 0.51; [95% CI: 0.30–0.87]), SHBG (OR: 0.49; [95% CI: 0.25–0.94]), and other exercises (OR: 0.52; [95% CI: 0.31–0.89])." (PMID 37624788, 2023). "In the FinnGen consortium, higher genetically predicted estradiol levels, SHBG levels, tea intake, and other exercises (e.g., swimming, cycling, keeping fit, and bowling) were significantly associated with a lower risk of urolithiasis." (PMID 37624788, 2023). "Similarly, the causal association of SHBG on urolithiasis remained significant after adjusting for tea intake (OR: 0.75; [95% CI: 0.58–0.97]), alcoholic drinks per week (OR: 0.75; [95% CI: 0.58–0.96]), and other exercises (OR: 0.70; [95% CI: 0.54–0.90])." (PMID 37624788, 2023). "The association between SHBG and urolithiasis is another complex causal risk factor to consider." (PMID 37624788, 2023). "In a case report, the association between serum gonadal steroids and urolithiasis in a 38-year old patient was confirmed after twice repeated estimation of testosterone, free testosterone, dihydrotestosterone, estradiol, and sex hormone binding globulin revealed hyperandrogenicity." (PMID 24695421, 2014). "However, after adjusting for potentially related exposures, the causal links between SHBG, estradiol, weekly alcohol consumption and urolithiasis did not prove independent of other factors." (PMID 37624788, 2023).
Uterine leiomyoma (3 papers, 2023 to 2025). The presence of a leiomyoma of the uterus. "The proteomic age acceleration increasing allele at POLR2A was associated with various traits, including decreased levels of sex-hormones (SHBG levels, total testosterone level), lower haematocrit and decreased risk for Leiomyoma of uterus." (PMID 40287427, 2025). "Uterine leiomyoma causes an increase in the level of sex hormone-binding globulin (SHBG), leading to an increase in the level of estrogens." (PMID 37024902, 2023).
varicocele (3 papers, 2016 to 2025). A condition characterized by the dilated tortuous veins of the spermatic cord with a marked left-sided predominance. "Finally, as suggested in many studies, SHBG levels in varicocele patients are higher than normal; the cause is unknown, but it may contribute to reduction of free androgen levels." (PMID 36303641, 2022). "Regarding varicocele analysis, the presence and grade of varicocele had no impact on TT and SHBG." (PMID 27256193, 2016).
Venous thrombosis (3 papers, 2016 to 2023). Formation of a blood clot (thrombus) inside a vein, causing the obstruction of blood flow. "Sex hormone-binding globulin (SHBG; rank 51), easily measured in routine laboratories, could serve as a marker for the risk of venous thrombosis." (PMID 27050193, 2016).
acanthosis nigricans (2 papers, 2010 to 2025). A melanotic cutaneous lesion that develops in the axilla and other body folds. "In obese, anovulatory PCOS women, weight loss restores ovulation and pregnancy rates, decreases insulin levels, diminishes acanthosis nigricans, lowers testosterone levels while raising sex hormone binding globulin (SHBG) levels, and improves psychological considerations." (PMID 22375190, 2010).
alcohol fatty liver disease (2 papers, 2021 to 2025). "Indeed, increasing SHBG is being considered as a therapeutic strategy for the treatment of non‐alcohol fatty liver disease." (PMID 34877821, 2021).
ankylosing spondylitis (2 papers, 2020 to 2023). An autoimmune chronic inflammatory disorder characterized by inflammation in the vertebral joints of the spine and sacroiliac joints. "SNN, a protein-coding gene playing a role in the toxic effects of organotin and endosomal maturation, has been proved to be linked to SHBG and a number of other autoimmune diseases including ankylosing spondylitis, psoriasis, ulcerative colitis, Crohn’s disease, and sclerosing cholangitis." (PMID 37644603, 2023).
Anorexia (2 papers, 2021 to 2024). Lack of desire to eat (loss of appetite). "One example is a longitudinal cohort of patients in whom SHBG levels were evaluated in anorexia and after a treatment to gain weight, showing that the levels of SHBG decrease in the gain weight therapy." (PMID 34335746, 2021).
Ascites (2 papers, 2021 to 2023). Accumulation of fluid in the peritoneal cavity (between the layers of the peritoneum that lines the abdomen). "Low TT, sex hormone binding globulin and FTI were associated with increased stage (of HBV-ACLF, ascites, and hepatic encephalopathy) and severity scores (Model for End-stage Liver Disease and Chinese Group on the Study of Severe Hepatitis B-ACLF scores)." (PMID 34872528, 2021). "Ascites were associated with low levels of free testosterone (p = 0.0015) and estradiol (p = 0.0003), but not with SHBG (p = 0.3036)." (PMID 36730272, 2023).
autism (2 papers, 2021 to 2023). Persistent deficits in social interaction and communication and interaction as well as a markedly restricted repertoire of activity and interest as well as repetitive patterns of behavior. "Both elevated maternal serum estradiol in males only and low maternal serum sex hormone binding globulin in both sexes are associated with increased autism risk." (PMID 37573326, 2023). "Autism status was significantly associated with decreased sex hormone binding globulin (AOR = 0.65 per 50 nmol/L, 95% CI 0.55–0.78, p < 0.001) overall and when stratified by sex and term pregnancy status." (PMID 37573326, 2023). "Likelihood of autism among offspring was associated with low SHBG and increased estradiol levels in early second trimester maternal serum." (PMID 37573326, 2023). "In crude and adjusted logistic regression analyses, autism status was significantly associated with decreased SHBG levels (OR = 0.66 per 50 nmol/L, 95% CI 0.56–0.77, p < 0.001; AOR = 0.65 per 50 nmol/L, 95% CI 0.55–0.78, p < 0.001, respectively)." (PMID 37573326, 2023). "SHBG levels demonstrated a significant inverse association with the presence of autism among offspring overall and across gestational age and sex categories." (PMID 37573326, 2023). "A pilot version of the current study found higher maternal serum estradiol levels, in combination with lower DHEA and SHBG levels, to be associated with increased likelihood of autism among term offspring." (PMID 37573326, 2023). "Understanding how prenatal maternal SHBG and estradiol levels are linked to autism among offspring could facilitate early detection screening strategies and foster the development of therapeutic interventions to optimize fetal health during this critical period of neurodevelopment." (PMID 37573326, 2023). "Current study findings support this prior work as the relationship between SHBG and autism likelihood was unchanged following adjustment for sex hormone levels." (PMID 37573326, 2023). "Both ANOVA and ANCOVA models yielded significant overall effects for autism/PNMS exposure on mean SHBG levels (F(3135) = 20.0 p < 0.001, F(8131) = 10.4 p < 0.001; (F(3131) = 12.3, p < 0.001)." (PMID 37573326, 2023). "The lack of association between SHBG levels and BMI in the autism group was particularly notable in the presence of PNMS exposure." (PMID 37573326, 2023). "Further work is needed to understand how lower SHBG and elevated estradiol levels may coincide with in utero processes that could collectively contribute to autism’s development." (PMID 37573326, 2023). "The inverse association between sex hormone binding globulin and autism was independent of PNMS exposure." (PMID 37573326, 2023). "Instead, SHBG levels in the autism group were low across the BMI range." (PMID 37573326, 2023). "Study findings suggest that maternal SHBG production is suppressed during the early second trimester of pregnancies associated with autism among offspring independent of fetal sex, gestational duration, BMI, sex hormone levels, and subsequent PNMS emergence." (PMID 37573326, 2023). "Although significant differences by autism status were identified in concentrations of SHBG overall and of estradiol in participant subgroups, differences by PNMS exposure failed to reach statistical significance, which may reflect insufficient statistical power." (PMID 37573326, 2023). "Low SHBG levels in the autism group regardless of BMI suggest that metabolic processes could be occurring during pregnancies associated with autism that supersede SHBG synthesis suppression by hepatic lipogenesis." (PMID 37573326, 2023). "While the post hoc analysis of SHBG and BMI demonstrated a significant association in the overall cohort, this relationship appeared to be driven entirely by the unaffected cohort and was absent in pregnancies from which offspring developed autism." (PMID 37573326, 2023).